RN7SKP188 (RN7SK pseudogene 188)
Gene: Miscellaneous RNA gene on chromosome 4 (167,662,986 to 167,663,302, forward strand). Ensembl gene ENSG00000222721.
Homologues: Orthologues: chimpanzee 7SK (83% identical). Paralogues in human: RN7SKP163 (56% identical), 7SK (55% identical), RN7SKP203 (55% identical), RN7SKP217 (54% identical), RN7SKP133 (54% identical), RN7SKP165 (54% identical), RN7SKP199 (54% identical), RN7SKP207 (54% identical), RN7SKP71 (54% identical), RN7SKP160 (53% identical), RN7SKP180 (53% identical), RN7SKP187 (53% identical), and 284 more.